SENP1 (SUMO specific peptidase 1)
Diseases named in the same sentence as SENP1 in open-access papers (continued):
Sharing a sentence is not in itself a finding about the gene and the disease.
tumor (continued). "In bladder cancer, the level of SENP1 in urine can detect tumor recurrence." (PMID 38389923, 2024). "However, the direct evidence of SENP1 function in tumor angiogenesis requires further investigation." (PMID 38389923, 2024). "Conclusively, SENP1 participates in tumor metabolism mainly through regulating glycolytic pathway." (PMID 38389923, 2024). "In summary, SENP1 plays an important role in tumor stemness and malignant development." (PMID 38389923, 2024). "Momordin Ic (MC), an SENP1 inhibitor, enhances SUMO2-pH3(Ser10) cytoplasmic accumulation in normoxic normal, high-glucose and hyper-osmotic conditions, thereby causing M-phase arrest and death of tumour cells." (PMID 36980166, 2023). "Besides, CD45 SUMOylation via SENP1-deficiency facilitates STAT3 dephosphorylation, suppressing tumor development by myeloid-derived suppressor cells (MDSC) infiltration." (PMID 37415251, 2023). "Additionally, SAE1 companied by E2 UBC9 and E3 ligase PIAS4 mediates AKT SUMOylation majorly at K276, regulating AKT activation and promoting tumor progression, which can be reversed by SENP1." (PMID 37415251, 2023). "It further indicates that SENP7 may be involved in LLPS generation, which is restricted by SENP1, due to which a few dormant stem-like tumour cells resist acute hypoxia challenge." (PMID 36980166, 2023). "Considering that MRTF-A has been reported that can promote both artery-specific differentiation and tumor cell metastasis, we questioned whether the suppressed angiogenesis following SENP1 knockdown may be mediated by its interaction with MRTF-A." (PMID 36979893, 2023). "Further, we have established subcutaneous tumor model and lung metastasis model, where we showed SENP1 downregulation could inhibit tumor development and metastasis into lung significantly." (PMID 35342335, 2022). "Furthermore, patients with higher plasma levels of exosome-derived SENP1 had worse tumor malignancy and overall survival rate." (PMID 36078118, 2022). "The genetic silencing of SENP1 or pharmacological inhibition with momordin Ic or triplotide reduces colony formation, migration, and invasion in PCa cell lines, as well as suppresses tumor growth in mouse PCa xenograft models." (PMID 34503213, 2021). "Moreover, MCL tumor growth in vivo was significantly suppressed after SENP1 knockdown in a xenograft nude mouse model." (PMID 34312374, 2021). "Based on these results, we concluded the potential involvement of SENP1 in tumor progression." (PMID 34276383, 2021). "SENP1 mRNA expression was also analyzed in 24 freshly frozen tumor lymph nodes from MCL patients and 13 freshly frozen normal lymph nodes or tonsil tissues by extracting data from GEO database, and was confirmed to be significantly upregulated in MCL specimens compared with that in normal specimens." (PMID 34312374, 2021). "Its anti-tumour activity may be related to the downregulation of SENP1 to restore the balance of SUMOylation and de-SUMOyaltion." (PMID 34830854, 2021). "Additionally, the expression of SENP1 is higher in tumor tissues than paracarcinoma tissues in patients with HCC." (PMID 35782332, 2021). "Meanwhile, tumor tissue and paired adjacent tissue specimens were obtained to evaluate SENP1 protein expression by immunohistochemistry (IHC) assay; among which, 102 pairs were used to detect SENP1 messenger RNA (mRNA) by reverse transcription quantitative PCR." (PMID 35782332, 2021). "Thus, SENP1 expression was higher in NSCLC tumor tissues compared with adjacent tissues in patients with surgical NSCLC receiving adjuvant chemotherapy." (PMID 35782332, 2021). "Relationship between SENP1 and tumor characteristics in 50 patients with HCC." (PMID 31969492, 2020). "Although it is intriguing to suggest that SENP1 may act a significant role in tumor progression, few of its downstream targets have been identified so far." (PMID 31969492, 2020).
tumor (continued). "Moreover, SENP1 knockout suppresses tumor development and progression while UBE2T overexpression or UBE2T K8R mutation in HCC cells displayed opposite impact." (PMID 31969492, 2020). "Therefore, this xenograft study verified the important role of SENP1 in driving tumor growth in vivo." (PMID 31969492, 2020). "Moreover, silencing of SENP1 promoted apoptosis, and inhibited the proliferation and migration of tumor cells." (PMID 28417919, 2017). "Next, we investigated if SENP1 regulates the EMT of tumor cells via controlling SMAD4 expression." (PMID 28417919, 2017). "Finally, SENP1 expression correlated positively with tumor pathological grade and was an indicator of poor overall survival and advanced tumor progression in ccRCC." (PMID 27741516, 2016). "SENP1 immunostaining was similarly linked to unfavorable tumor features in subsets of both ERG negative and ERG positive cancers." (PMID 26202067, 2015). "In addition to these cell cycle regulators, silencing the expression of SENP1 also significantly increased IR-induced γ-H2AX expression, which has been revealed to be positively associated with tumor radiosensitivity." (PMID 24137315, 2013). "Its anti-tumor activity may be attributed to mechanisms involving down-regulation of SENP1 that restores SUMOylation and deSUMOyaltion balance and negative regulation of AR and c-Jun expression that inhibits the AR and c-Jun mediated transcription in PCa." (PMID 22666381, 2012). "To verify that SENP1 could be a predictor of long-term prognosis in ESCC patients, we used univariate COX regression analysis to validate the patients’ age, gender, lymph node metastasis rate, pathological T-stage, pathological N-stage, tumor differentiation, and SENP1 expression, respectively." (PMID 38954215, 2025). "Interestingly, previous studies have also reported that SENP1 enhances tumor cell glycolysis." (PMID 38822351, 2024). "Besides, the expression of SENP1 in precancerous prostatic tissue was significantly up‐regulated compared to the adjacent normal prostate epithelia, indicating that SENP1 could regulate the development of tumours." (PMID 34120412, 2021). "To further test the SENP1 induction by platinum drugs in vivo, we measured SENP1 protein levels in IGROV1 xenograft tumors by using immune histochemistry (IHC) in implanted immunodeficient nude mice that were treated with carboplatin at 20 mg/kg or 60 mg/kg after tumor was developed." (PMID 33795649, 2021). "We did not observe any association between: progesterone receptor status, HER2 expression and tumor grade described by Bloom-Richardson grading system, and the distribution of genotypes and frequency of alleles for these polymorphisms of the SENP1 and SENP2 genes (data not shown)." (PMID 27178176, 2016). "Here, consistent with our speculation, integrated gene expression and metabolomic analyses of 36 matched pairs of ccRCC tumor and adjacent normal tissues revealed that patients with high SENP1 expression level also exhibit enhanced glycolysis, illustrated by elevated levels of lactate and pyruvate." (PMID 27741516, 2016). "We also found that SENP1 and OCT4/EMT expression levels were positively correlated with early tumor recurrence in patients with HCC." (PMID 41438340, 2026). "In this study, we demonstrated that HBx-induced SENP1 expression regulates CSC-related properties and tumor metastasis, particularly in HBV-related HCC, in clinical, in vitro, and in vivo settings." (PMID 41438340, 2026). "Elevated SENP1 expression was further validated in the GSE76427 cohort, showing significantly higher SENP1 mRNA levels in tumor tissues vs. adjacent non-tumor tissues." (PMID 41438340, 2026). "Paired tumor and peritumor tissues from 211 patients with HCC were analyzed to correlate SENP1, OCT4, SNAIL, PIN1, and TWIST expression with overall survival (OS) and disease-free survival (DFS) using a Kaplan-Meier survival analysis." (PMID 41438340, 2026).
tumor (continued). "Immunohistochemical (IHC) staining confirmed significantly higher expression of SENP1 and the OCT4 and CD133 stemness-related proteins in HBV-HCC tumor tissues compared to NBNC-HCC tumor tissues." (PMID 41438340, 2026). "As well, xenograft tumours derived from KMT2D‐ and YBX1‐knockdown cells expressed significantly lower levels of c‐Myc and SENP1." (PMID 38967349, 2024). "In triple-negative breast cancer (TNBC), overexpressed SENP1 promotes CSN5-mediated ZEB1 protein degradation via deSUMOylation of GATA1, and ultimately enhances metastasis and invasion of tumor cells." (PMID 37415251, 2023). "In this study, we explored the relationship between SENP1 expression and TNBC metastasis, using TNBC tumor tissues as well as cell lines." (PMID 35342335, 2022). "Then, IHC staining of SENP1 and UCHL1 was performed to evaluate their physiological relevance to AR and tumour progression." (PMID 35452181, 2022). "Our in vivo studies also indicated that reduction in SENP1 expression upregulated GATA1 SUMOylation, and thus resulted in decreased expression of CSN5 and ZEB1 in the tumor microenvironment, which decelerated TNBC progression and metastasis." (PMID 35342335, 2022). "We established subcutaneous mouse models and lung metastasis nude mouse models using the MDA-MB-231, shRNA-NC-MDA-MB-231 and shRNA-SENP1-MDA-MB-231 cell lines, to explore the role of SENP1 in tumor formation and metastasis in vivo." (PMID 35342335, 2022). "We further showed that by reducing SENP1 in TNBC subcutaneous mouse models and lung metastasis models, tumor growth and metastasis were significantly inhibited." (PMID 35342335, 2022). "The knockdown of SENP1 decreases proliferation, colony formation, invasion, and stemness of HCC cells, and reduces tumor growth in mouse xenograft models, indicating SENP1 as a potential therapeutic target in HCC." (PMID 34503213, 2021). "SENP1 is also upregulated in TNBC tissues, and depletion of SENP1 attenuates TNBC cell proliferation and migration, tumor growth and metastasis." (PMID 33968766, 2021). "Further subgroup analyses indicated that SAE1 and UBE2I had differential expressions with different stages, while SENP1, USPL1, SENP2, SENP5, SAE1, UBA2, and UBE2I had differential expressions with different tumor grades." (PMID 34267779, 2021). "SENP1-Sirt3 axis promotes FAO-fuelled OXPHOS and reduces YME1L1-mediated OPA1 cleavage in T cell memory development and T-cell-mediated anti-tumour immunity." (PMID 34272364, 2021). "Silencing of SENP1 reduces proliferation, invasion and colony formation of TNBC cell lines and reduces tumor size and lung metastases in a TNBC mouse xenograft model." (PMID 34503213, 2021). "The SENP1 expression level positively correlated with the expression levels of UBN1, SP3, SAP130, NUP98, NUP153 in 32 tumor types." (PMID 34276383, 2021). "In conclusion, our study demonstrated that SENP1 and UBE2T were positively related and functioned as tumor promoters." (PMID 31969492, 2020). "SENP1 silencing leads to the increased expression of E-cadherin, and inhibition of EMT of tumor cells." (PMID 28417919, 2017). "Taken together, these studies suggest that in low-expressing SENP1 LNCaP cells, SENP1 over-expression down-regulated SMAD4 protein expression and promoted EMT of tumor cells." (PMID 28417919, 2017). "Consistent with an inhibition of SENP1 activity, Mc treatment also lead to the accumulation of SUMO1- and SUMO2/3-modified proteins in PC3 tumor xenografts." (PMID 27449295, 2016). "Scenario 3 included SENP1 expression, preoperative PSA, clinical tumor stage (cT stage) and Gleason grade obtained on the prostatectomy specimen." (PMID 26202067, 2015). "Moreover, SENP1 enhanced cell proliferation and migration of ESCC cell lines in vitro, as well as promoted tumor growth in vivo." (PMID 38954215, 2025). "In addition, the effects of SENP1 on AML energy metabolism and the tumor microenvironment need to be further studied." (PMID 38822351, 2024).
tumor (continued). "The SUMOylated RNF168 catalyzed by SENP1 prevents the occurrence of LLPS, allowing RNF168 to be recruited to DNA damage sites for nonhomologous DNA end-joining, thereby maintaining genomic stability and even making tumor cells resistant to chemotherapy." (PMID 39749343, 2024). "Our observations so far suggested that SENP1 downregulation drove SUMOylated pH3(Ser10) into an LLPS-like phenotype in normoxic conditions, thereby inhibiting the cell proliferation functions of pH3(Ser10) and retarding tumour growth." (PMID 36980166, 2023). "SENP1 RNA expression is correlated positively with HIF2α, but not HIF1α, RNA levels in these tumor samples." (PMID 36284084, 2022). "Claudin 6 (CLDN6) appears to be able to regulate the HIF-1α pathway through SENP1 in BC cells and BC patients with primary CLDN6 loss are more prone to have tumor metastasis, due to a lack of feedback mechanism that impairs HIF-1α stability." (PMID 35465332, 2022). "There is yet no sufficient Pan-Cancer evidence on the relation between SENP1 and different tumor types based on clinical data." (PMID 34276383, 2021). "A possible reason could be that: SENP1 reflected the higher proliferation rate of cells; meanwhile, the proliferation rate in NSCLC cells in the tumor tissue was increased than that in the adjacent tissue cells." (PMID 35782332, 2021). "Moreover, SENP1, USPL1, SENP2, SENP5, SAE1, UBA2, and UBE2I had differential expressions with different tumor grades." (PMID 34267779, 2021). "Accordingly, clinical data indicated that patients with higher expression level of SENP1 generally suffered from larger tumor size, poorer histological characteristics, later TNM stage and more tumor number, which is also in accordance with the results of overall survival rate." (PMID 31969492, 2020). "Since SENP1 can and does regulate multiple mechanisms simultaneously, it is highly probable that the absence of carcinoma in the SENP1-Tg mouse model is due to a concurrent SENP1-regulation of unidentified tumor-suppressive pathway(s)." (PMID 27852060, 2017). "In such a scenario, the additional PTEN deletion would result in such a strong disruption of cancer cell physiology that SENP1 expression no longer has a critical additional effect on tumor aggressiveness." (PMID 26202067, 2015). "Importantly, no apparent tumor progression was observed in the SENP1-silenced groups throughout the treatment period, indicating effective suppression of tumor growth." (PMID 41438340, 2026). "To determine whether the RNA data can be extended to protein expression levels in ccRCC, we performed immunohistochemistry (IHC) analysis using anti-SENP1, HIF1α, and HIF2α antibodies with a custom tissue microarray (TMA) containing 190 benign and 471 malignant ccRCC tumor samples." (PMID 36284084, 2022). "Our data suggest that SENP1 expression in HIF2αhi/HIF1αlo cells might enhance the stemness of tumor cells without increasing the proliferation of overall tumor epithelial cells." (PMID 36284084, 2022). "We checked the distribution of genotypes and frequency of alleles of the SENP1 and SENP2 genes polymorphisms in groups of patients with different hormone receptor status, patients with positive and negative lymph node status and patients with different tumor grade." (PMID 27178176, 2016). "We also checked the distribution of genotypes and frequency of alleles of the SENP1 and SENP2 genes polymorphisms in groups of patients with different hormone receptor status, patients with positive and negative lymph node status and patients with different tumor grade." (PMID 27178176, 2016). "We also showed that overexpression of SENP1 in mouse prostate induced PIN lesions, but no tumor formation in the transgenic model." (PMID 27659494, 2016). "In this subgroup, the prognostic role of SENP1 expression was independent of the preoperative PSA level, tumor stage, Gleason grade, and the status of the resection margin." (PMID 26202067, 2015).
tumor (continued). "We found significant differences in urinary content of hTERT (p < 0.001), SENP1 (p < 0.001), MCM5 (p < 0.001), and PPP1CA (p < 0.001) transcripts, when comparing urine samples from patients with and without tumor present in the bladder." (PMID 21106093, 2010). "Overexpression of SENP1 in mouse prostate induced PIN lesions, but not tumor formation." (PMID 27659494, 2016). "In addition, we observed a trend showing elevated SENP1 expression in the ccRCC with advanced stages (stage III and IV, 80.0%) than those with early stages (stage I and II, 67.3%), and with tumor invasion (85.7%) than without tumor invasion (68.3%), although there is no statistical significance." (PMID 27741516, 2016).